RPL15 (ribosomal protein L15)
Diseases named in the same sentence as RPL15 in open-access papers (continued):
Sharing a sentence is not in itself a finding about the gene and the disease.
melanoma (4 papers, 2021 to 2025). A malignant, usually aggressive tumor composed of atypical, neoplastic melanocytes. "eL15/RPL15 knockdown in a mouse model for melanoma resulted in increased secretion of cell stress signaling molecules known as damage-associated molecular patterns (DAMPs) that activate antitumor immune responses and sensitize tumors to PD-1 blockade." (PMID 37047306, 2023). "RPL15-knockdown B16-F10 melanoma tumors were sensitized to anti-PD-1 antibody, suggesting that RPL15 inhibition may have the potential to improve immune checkpoint inhibitor efficacy." (PMID 41276688, 2025). "Moreover, RPL15 knockdown in B16-F10 murine melanoma cells sensitized B16-F10 tumors to anti-PD-1 antibody treatment, suggesting that targeting RPL15 may improve ICI efficacy." (PMID 41276688, 2025).
ovarian carcinoma (3 papers, 2012 to 2024). A malignant neoplasm originating from the surface ovarian epithelium. "A set of eight biomarkers: NKIRAS1/RPL15, THRB, RBPS3 (CTDSPL), IQSEC1, NBEAL2, ZIC4, LOC285205 and FOXP1, was identified as the most prominent set capable to detect both early and late stages of ovarian cancer." (PMID 23202957, 2012).
pancreatic cancer (3 papers, 2015 to 2023). "have reported that a low expression of RPL15 is related to a poor prognosis, as well as cell invasion and metastasis in pancreatic cancer patients." (PMID 34873618, 2021). "First, we detected RPL15 expression in six pancreatic cancer cell lines and one normal pancreatic cell line both at mRNA and protein level." (PMID 26498693, 2015). "Results showed that RPL15 was significantly decreased in the pancreatic cancer cell lines, especially in cell line SW1990." (PMID 26498693, 2015). "Besides, we determined the molecular mechanism by which overexpression of RPL15 inhibited pancreatic cancer cell invasion." (PMID 26498693, 2015). "Here we showed that the overexpression of RPL15 could significantly upregulate epithelial markers and downregulate mesenchymal markers in pancreatic cancer cells." (PMID 26498693, 2015). "Hence, the impaired pancreatic cancer cell invasion ability due to overexpression of RPL15 could be accounted, at least in part, for the inhibition of EMT process." (PMID 26498693, 2015). "Furthermore, we found that overexpression of RPL15 could inhibit pancreatic cancer cell invasion and metastasis ability via suppressing EMT process." (PMID 26498693, 2015). "RPS8, RPL15 and RPL21 could also serve as biomarkers in pancreatic cancer." (PMID 34873618, 2021).
colorectal cancer (2 papers, 2015 to 2024). A primary or metastatic malignant neoplasm that affects the colon or rectum. "In the context of gastric cancer, RPL15, RPL6 and RPS13 exhibited upregulated expressions, while in colorectal cancer, RPS18, RPS23, RPL28 and RPL32 were found to be downregulated, implicating these ribosomal proteins as potential diagnostic markers for gastric and colorectal cancers, respectively." (PMID 39684863, 2024).
glioma (2 papers, 2021 to 2023). A benign or malignant brain and spinal cord tumor that arises from glial cells (astrocytes, oligodendrocytes, ependymal cells). "In general, circ-RPL15 might promote glioma progression by suppressing miR-146b-3 and thus upregulating VEGFA activity." (PMID 37234708, 2023). "Overexpression of circ-RPL15 was observed in glioma tissues and cell lines." (PMID 37234708, 2023). "Knockdown of circ-RPL15 decreased glioma cell viability and migratory ability." (PMID 37234708, 2023).
Parkinson’s (2 papers, 2016 to 2024). "It has also been reported that RPL15 is closely related with parkinson’s disease and other brain disorders." (PMID 27050411, 2016). "Finally, although the EEF1A1, RPL12 and RPL15 genes have not been directly linked to ALS, they have been associated with other neurological diseases, such as Parkinson’s and Alzheimer’s." (PMID 38540795, 2024).
Alzheimer disease (1 paper, 2024). A progressive, neurodegenerative disease characterized by loss of function and death of nerve cells in several areas of the brain leading to loss of cognitive function such as memory and language. "Conversely, the RPL12 and RPL15 genes exhibited significant up-regulation in brain capillary samples obtained from patients diagnosed with Alzheimer’s disease." (PMID 38540795, 2024).
breast tumor (1 paper, 2024). "RPL15 (eL15) and RPL35 (uL29) expression in circulating breast tumor cells is correlated with increased proliferation and reduced apoptosis, as well as higher metastatic capacity." (PMID 38729158, 2024).
cardiomyopathy (1 paper, 2025). A disease of the heart muscle or myocardium proper. "Chord mapping revealed core genes (e.g., NDUFB6, RPL15, ATP5PB) involved in multiple interconnected pathways.DO analysis confirmed enrichment in cardiomyopathy, coronary artery disease, and myocardial infarction, supporting the cardiovascular specificity of the identified genes." (PMID 41200169, 2025).
cyst (1 paper, 2025). A sac-like closed membranous structure that may be empty or contain fluid or amorphous material. "Interestingly, the signal intensities of 5.8S, 18S, 28S rRNAs, and Rpl15 were low in a portion of wild-type 1- to 2-cell cyst spermatogonia, suggesting the presence of two populations also in the rRNA concentrations (low and high) in the 1- to 2-cell stage." (PMID 40705004, 2025).
glaucoma (1 paper, 2023). Increased pressure in the eyeball due to obstruction of the outflow of aqueous humor. "Next, the GWAS analysis was conducted to confirm that the pathogenic regions of HSPA8 and RPL15 in glaucoma were located on chromosome 11 and 3, respectively, and significant SNPs corresponding to 2 hub genes were found." (PMID 37968618, 2023). "The expression levels of hub genes were significantly correlated with the expression levels of multiple glaucoma-related genes, among which HSPA8 was significantly negatively correlated with CYP1B1 (Pearson r = − 0.48) and RPL15 was significantly positively correlated with WDR36 (Pearson r = 0.58)." (PMID 37968618, 2023).
metastatic cancer (1 paper, 2021). A carcinoma which has spread from the original site of growth to another anatomic site. "Surprisingly, RPL27A was well colocalized with RPL15 only in metastatic cancer cells; however, in primary cancer cells, the transcripts of the two genes were low and rarely colocalized." (PMID 34497807, 2021). "The split UMAP visualization of RPL27A and RPL15 expressions in primary and metastatic cancer cells confirmed these differences." (PMID 34497807, 2021).
Shwachman-Diamond syndrome (1 paper, 2018). "Gene expression profiles of bone marrow mononuclear cells from patients with Shwachman-Diamond syndrome revealed significant downregulation of RP genes, including RPS9, RPS20, RPL6, RPL15, RPL23, and RPL29, or upregulation of RPS27." (PMID 29954325, 2018).
triple-negative breast carcinoma (1 paper, 2023). An invasive breast carcinoma which is negative for expression of estrogen receptor (ER), progesterone receptor (PR), and human epidermal growth factor receptor 2 (HER2). "The protein is also implicated in colon carcinogenesis, and recently, the expression of the ribosomal protein gene RPL15 was found to be significantly upregulated in metastatic triple-negative breast cancer cells." (PMID 36838813, 2023).
cancer (24 papers, 2006 to 2025). A tumor composed of atypical neoplastic, often pleomorphic cells that invade other tissues. "We previously showed that topotecan, a chemotherapeutic drug and topoisomerase I (TOP1) inhibitor, binds to ribosomal protein RPL15 and induces the secretion of DAMPs from cancer cells, which activate cGAS-STING signaling in dendritic cells." (PMID 41276688, 2025). "This suggests cancer cells become resistant to SN38-PROTAC because hCRBN expression is required for RPL15 degradation and DAMP-mediated STING activation." (PMID 41276688, 2025). "RPL15 is upregulated in a variety of cancer cells, such as gastric cancer, triple-negative breast cancer, and leukemia." (PMID 38002277, 2023). "RPL15, a large ribosomal subunit protein, is significantly upregulated in human cancer tissues and cultured cell lines, and it is closely correlated with clinicopathological characteristics." (PMID 36118863, 2022). "Colony formation, CCK-8, flow cytometry, Wound healing and Transwell invasion assays, were used to detect the carcinoma progression of HCC cells with RPL15 overexpression or knockdown in vitro." (PMID 35410346, 2022). "This was further confirmed in our study by the data that an increased expression of Rpl15 gene was found in the cancer cells." (PMID 34497807, 2021). "Surprisingly, two ribosomal protein genes, Rpl27a and Rpl15, were significantly upregulated in the cancer cells in all the TNBC models." (PMID 34497807, 2021). "Among the deregulated gene candidates, ribosome protein genes were highly involved in TNBC development and metastasis, and two of the most consistent genes between mouse models and human cancer were RPL15 and RPL27A." (PMID 34497807, 2021). "The results were consistent with IHC and showed that there is about a 1.8 fold higher level of RPL15 expression in total cancer tissue than that of adjacent tissue." (PMID 31523176, 2019). "As a component of the ribosomal 60S subunit, RPL15 was reported to be dysregulated in many types of diseases and cancers." (PMID 26498693, 2015). "Our recent studies showed that topotecan, a TOP1 inhibitor, binds to ribosomal protein RPL15, resulting in the induction of ribosomal stress and the secretion of DNA-containing exosomes as DAMPs from cancer cells, which activate STING-dependent antitumor immune responses." (PMID 41276688, 2025). "Ribosomal RNA processing 15 homolog (RPL15) promotes metastatic growth in multiple cancer organs, and enhancing the altered expression of RPL15 may alter the translational efficiency of ribosomes." (PMID 38002277, 2023). "In addition, further phage-peptide clones with homology to YBX1, RPL15 and CHRNA2 have been associated with cancer and other disease." (PMID 26039628, 2015). "It has been reported that RPL15 may be dysregulated in various types of cancers, including esophageal, pulmonary and cutaneous carcinoma." (PMID 26498693, 2015). "It was reported that RPL15 is dysregulated in various type of cancers." (PMID 26498693, 2015). "RPL15 was found expressed predominantly in the cytoplasm of cells in gastric mucosa and cancer." (PMID 16608517, 2006). "Furthermore, Rpl15 siRNA-mediated downregulation induces cell cycle arrest by inhibiting cyclin-dependent kinases and results in a significant increase in the percentage of apoptosis in cancer cells." (PMID 34848840, 2021). "Our results indicate that SN38-PROTAC degrades RPL15 protein and shows the potential to enhance ICI therapeutic efficacy in PD-1-resistant cancer with low cytotoxicity." (PMID 41276688, 2025). "Our results indicate that SN38-PROTAC, which induces RPL15 degradation, has the potential to enhance ICI efficacy in PD-1-resistant cancer with low cytotoxicity." (PMID 41276688, 2025). "Ribosomal protein genes, represented by RPL27A and RPL15, showed significantly upregulated expression in metastatic TNBC cancer cells." (PMID 34497807, 2021).
cancer (continued). "Examples of RPLs and RPSs include RPL15, RPL19, RPS6 and RPS15A, which have been associated with a negative prognosis in malignant neoplasms of the digestive system." (PMID 38804617, 2024). "We selected novel epigenetic markers including NKIRAS1/RPL15, THRB RBPS3 (CTDSPL), IQSEC1, NBEAL2, ZIC4, LOC285205, CGGBP1, EPHB1 and FOXP1 that allowed detection of cancer in ovarian biopsies on all stages with sensitivity equal to (72 ± 11)% and specificity (94 ± 5)%." (PMID 23202957, 2012). "Interestingly, in our study, ribosomal protein L15 was identified as a Kpnβ1-binding partner in 2 of the 3 cancer cell lines, but not the non-cancer hTERT-RPE-1 cells." (PMID 36418423, 2022).
tumor (23 papers, 2006 to 2025). "Therefore, Rpl15 is the most critical ribosomal protein in carcinogenesis, increasing the risk of tumor formation in IVF-derived offspring." (PMID 34848840, 2021). "Anchorage-independent growth could be a sensitive marker for tumor growth in vivo; therefore, we examined whether interference of RPL15 expression would cause an inhibition of SGC7901 cell growth in soft agar." (PMID 16608517, 2006). "Studies have revealed that RPs such as RPL15 are key in advancing metastasis, particularly in circulating tumor cells (CTCs), through the amplification of protein translation." (PMID 38787142, 2024). "RPL15 knockdown increased the cytotoxic T lymphocytes and decreased the T-regulatory cells to enhance anti-tumor immune response." (PMID 37968618, 2023). "In HCC, RPL15 was shown to play crucial roles in tumor progression and metastasis, and as such, it is considered a promising candidate for targeted therapies." (PMID 36838813, 2023). "Tumor volumes and weights in RPL15-knockdown group were significantly reduced compared to the NC group." (PMID 35410346, 2022). "This is in line with the observation that ectopic expression of RPL15 increases overall expression in breast-circulating tumor cells." (PMID 36192788, 2022). "Rpl15 plays a critical role in accelerating tumor progression by selectively enhancing the translation of other ribosomal proteins and cell cycle/apoptosis regulators." (PMID 34848840, 2021). "For example, upregulation of expression of ribosomal proteins uL6 (gene RPL9), eL15 (RPL15), and eL39 (RPL39) is associated with increased tumor growth and metastasis in some cancers." (PMID 33990576, 2021). "Another most recent study revealed that RPL15-overexpressing circulating tumor cells markedly increased metastatic burden in mice." (PMID 34497807, 2021). "The tissue microarray analysis results also confirmed that RPL15 protein displayed lower expression in tumor tissues than peritumoral tissues (p < 0.0001)." (PMID 26498693, 2015). "We noted that RPL15, a ribosomal protein well known to be overexpressed and to enhance tumor invasiveness in metastatic breast cancer, did not exhibit significant changes in our data, indicating its potential ribosomal heterogeneity across different tumor types." (PMID 38787142, 2024). "Moreover, the multivariable Cox regression analysis also confirmed that RPL15 expression, age, tumor size, lymphatic metastasis, distant metastasis and histological differentiation were independent predictors of PDAC patients' overall survival after pancreatectomy." (PMID 26498693, 2015). "We next investigate whether SN38-PROTAC-induced RPL15 degradation and DAMP secretion contribute to antitumor immune responses in the B16-F10 tumor-bearing mouse model." (PMID 41276688, 2025). "The results demonstrated that the expression level of RPL15 was significantly reduced in tumor tissues compared with normal pancreatic epithelium in both independent datasets (p < 0.0001)." (PMID 26498693, 2015). "The result showed that RPL15 expression did not correlate with differentiation grade, Tumor-Node-Metastasis stage, gross type, or metastasis with a statistic p > 0.05 in each parameter (data not shown)." (PMID 16608517, 2006). "We infer that HIVEP3, by collaborating with the ribosomal protein (RP) family, such as RPL15, RPL34, and RPS24, could regulate tumor cell cycle and apoptosis and promote tumor proliferation and infiltration metastasis, angiogenesis, or other malignant biological behaviors." (PMID 35535739, 2022).
infection (1 paper, 2020). The state of being infected such as from the introduction of a foreign agent such as serum, vaccine, antigenic substance or organism. "We found that ribosomal proteins, such as ribosomal protein S20 (RPS20), S14 (RPS14), L15 (RPL15), and S14 precursors, which are generally expressed in bradyzoites, were highly expressed in the ME49 strain 72 h post-infection, indicating bradyzoite formation in the brain organoids." (PMID 32820712, 2020).
neurodegenerative disease (1 paper, 2023). A disorder of the central nervous system characterized by gradual and progressive loss of neural tissue and neurologic function. "The expression of RPL15 was closely related to several neurodegenerative diseases, such as AD and PD." (PMID 37968618, 2023).
neurological diseases (1 paper, 2024). "Additionally, while no studies directly related to ALS were discovered, other studies related to other neurological diseases were found in the cases of the EEF1A1, COX5A and RPL12 and RPL15 genes." (PMID 38540795, 2024).
RPL15 also shares sentences with these, for which no sentence is quoted: esophageal cancer (3 papers); cutaneous squamous cell carcinoma (2); anemia (1); bone marrow disorder (1); brain disorder (1); chronic lymphocytic leukemia (1); coronary artery disease (1); COVID-19 (1); liver cancer (1); lymph node metastasis (1); multiple myeloma (1); myocardial infarction (1); systemic lupus erythematosus (1); T-lymphoma (1).